IL33 (interleukin 33)
Diseases named in the same sentence as IL33 in open-access papers (continued):
Sharing a sentence is not in itself a finding about the gene and the disease.
leukemia (18 papers, 2016 to 2025). A malignant (clonal) hematologic disorder, involving hematopoietic stem cells and characterized by the presence of primitive or atypical myeloid or lymphoid cells in the bone marrow and the blood. "In this study, we provided the first evidence that systemic administration of recombinant IL-33 dramatically inhibits leukemia growth and prolonged the survival associated with augmented anti-leukemia immune responses of CD8+ T cells." (PMID 27517629, 2016). "Notably, IL-33 administration licensed DCs from tumor-bearing mice to overwhelm the tolerance of leukemia-specific CD8+ T cells by causing expression of several costimulatory molecules." (PMID 31652497, 2019). "IL-33 is believed to enhance levels of 15-lipoxygenase 1 in acute myeloid (eosinophilic) leukemia cells, a compound known to facilitate inflammatory processes in eosinophilic CRSwNP patients." (PMID 35752781, 2022). "To decipher the mechanism of IL-33/p38 MAPK in regulating leukaemia cell survival, we assessed the cell cycle status in BM cells from children with first recurrence of ALL by flow cytometry." (PMID 34435521, 2021). "Further investigation revealed that the IL-33/IL1RL1 axis can inhibit leukemia cell apoptosis via phosphorylation of p38 MAPK." (PMID 33324412, 2020). "In chronic myeloid leukemia (CML) cells expressing BCR-ABL1, IL-33 increases the proliferation and helps leukemia cells exert resistance to the inhibitor imatinib." (PMID 33324412, 2020). "We found that treatment of Cbfb-MYH11+ leukemia cells with exogenous IL-33, the only known IL1RL1 ligand, reduced apoptosis and proliferation, and increased serial replating ability." (PMID 30742053, 2019). "Augmentation of the immune response by systemic administration of recombinant IL-33 was shown to inhibit leukemia growth and prolong the survival of leukemia bearing mice." (PMID 31231372, 2019). "To test if the increase in colony number is related to increased proliferation, we measured BrdU incorporation and cell cycle status on leukemia cells treated with IL-33." (PMID 30742053, 2019). "The expression of IL1RL1 (the gene encoding receptor for IL33), which was reported co-expressed with RUNX1 in mouse and human leukemia cells, was also positively correlated with that of RUNX1." (PMID 31501518, 2019). "IL-33 inhibits leukemia growth, improves mice survival rate through CD8+ T cells and synergizes with PD-1 blockade to promote tumor rejection." (PMID 30483263, 2018). "In the aggressive C1498 acute myeloid leukemia (AML) model, IL-33 treatment significantly increased the percentage of effector memory liver CD8+ T cells leading to delayed leukemia development and improved overall survival." (PMID 30483263, 2018). "In this study the increased CD8+ T cells activation level up-regulates PD-1/PD-L1 expression in vivo, therefore combination of PD-1 blockade and IL-33 treatment further improves survival of leukemia-bearing mice." (PMID 30483263, 2018). "To examine the potential anti-leukemia effect of exogenous IL-33, we challenged the C57BL/6 mice with the murine acute myeloid leukemia cell line C1498.GFP." (PMID 27517629, 2016). "Given the importance of CD8+ DCs in the immune recognition of AML, we examined the CD8+ DC accumulation in leukemia-bearing mice following IL-33 treatment." (PMID 27517629, 2016). "Our data suggest that reversing DC dysfunction by exogenous IL-33 treatment also contributes to the enhanced leukemia-reactive T cell-mediated antitumor immune response." (PMID 27517629, 2016). "Given the induction of IL-33 on PD-1/PD-L1 expression, we examined the anti-leukemia activity of combination treatment with PD-1 blockade plus IL-33 administration." (PMID 27517629, 2016). "Exogenous IL-33 treatment enhanced anti-leukemia activity by increasing the expansion and IFN-γ production of leukemia-reactive CD8+ T cells." (PMID 27517629, 2016).
leukemia (continued). "To check the effect of IL-33 on PD-1/PD-L1 pathway in C1498.SIY leukemia model, we initially examine the PD-L1 expression on leukemia cells and DCs following IL-33 treatment." (PMID 27517629, 2016). "On day 13, the leukemia burden in control mice was three times more than that in IL-33-treated mice." (PMID 27517629, 2016). "To further dissect the anti-leukemia effect of IL-33, we examined the frequency and function of effector CD8+ T cells at early (day 9) and late (day 14) stages." (PMID 27517629, 2016). "Using an established murine acute myeloid leukemia (AML) model, we here show that systemic administration of recombinant IL-33 dramatically inhibits the leukemia growth and prolongs the survival of leukemia-bearing mice in a CD8+ T cell dependent manner." (PMID 27517629, 2016). "CD8+ T cell depletion diminished the anti-leukemia effect of exogenous IL-33, as reflected by progressive leukemia burden in peripheral blood and liver comparable with those of the control PBS group." (PMID 27517629, 2016). "Our data establish a role of exogenous IL-33 in reversing T cell tolerance, and suggest its potential clinical implication into leukemia immunotherapy." (PMID 27517629, 2016). "We show in this study that systemic administration of recombinant IL-33 inhibited leukemia growth and prolonged the survival of C1498 leukemia-bearing mice in a CD8+ T cell dependent manner." (PMID 27517629, 2016). "In contrast, IL-33 treatment significantly extended the life span of leukemia-bearing mice from a median survival 16 days to 21 days." (PMID 27517629, 2016). "To further determine the ability of exogenous IL-33 to overcome the peripheral T cell tolerance in leukemia-bearing hosts, we carried out an adoptive transfer model using SIY-specific 2C TCR transgenic CD8+ T cells." (PMID 27517629, 2016). "In this study, we investigated how stem cell leukemogenesis is initiated and maintained and we hypothesized that a stress-induced intrinsic IL-33/Il1rl1 autocrine loop will initiate and promote leukemia stemness." (PMID 40659660, 2025). "Moreover, in accordance with the upregulated IL1RL1 on leukaemia cell surface, we observed a remarkably increased serum IL-33 level in primary ALL patient samples in comparison to HD." (PMID 34435521, 2021). "Furthermore, our observation was consistent to our previous study, in which IL-33 induced an increase of S-phase cells, thus promoting proliferation in both primary mouse leukaemia cells and patient AML samples." (PMID 34435521, 2021). "Together, our data suggest that IL-33 might work with IL-6 in the local and systemic circulation to support the maintenance of leukemia cells." (PMID 33324412, 2020). "In addition, we found that the addition of exogenous IL-33 promotes the mRNA expression of the inflammatory cytokine, IL-6, in mouse leukemia cells by in vitro analysis." (PMID 33324412, 2020). "We next sought to examine whether IL-33 could enhance IL-6 release by leukemia cells using the same patient group." (PMID 33324412, 2020). "IL-33 could likewise increase T cell activation to promote graft- vs.-leukemia (GVL) reactions while decreasing fatal graft-vs.-host- disease (GVHD)." (PMID 30416507, 2018). "The data indicate that IL-33 may improve the overall survival by boosting the anti-leukemia immunity through CD8+ T cells." (PMID 27517629, 2016). "Moreover, IL-33 treatment increased the percentage of IFN-γ producing CD8+ T cells in liver of these leukemia-bearing mice at both early and late stages." (PMID 27517629, 2016). "Interestingly, we found that IL-33 treatment promoted anti-leukemia activity but induced the PD-L1 expression on leukemia cells and PD-1 expression on CD8+ T cells." (PMID 27517629, 2016). "Similarly, IL-33 treatment prolonged the life span of leukemia-bearing mice from a median survival 18 days to 36 days, while being more effective in inhibiting the growth of C1498." (PMID 27517629, 2016).
leukemia (continued). "Importantly, IL-33 treatment effectively licensed DCs from tumor-bearing mice to overcome the tolerance of leukemia-specific CD8+ T cells by inducing expression of different costimulatory molecules." (PMID 27517629, 2016). "Moreover, IL-33 promoted dendritic cell (DC) maturation and activation in favor of its cross presentation ability to evoke a vigorous anti-leukemia immune response." (PMID 27517629, 2016). "As host DCs may mediate T cell tolerance in AML, we hypothesized that exogenous IL-33 may work through DCs to reverse leukemia-reactive CD8+ T cell dysfunction." (PMID 27517629, 2016). "On the other hand, IL-33 can directly stimulate T cell production of IFN-γ that may in turn induce PD-L1 expression on leukemia cells." (PMID 27517629, 2016). "We demonstrate that IL-33-mediated anti-leukemia activity depends upon CD8+ T cells." (PMID 27517629, 2016). "Importantly, we showed that combining IL-33 treatment with PD-1/PD-L1 blockade conferred superior anti-leukemia activity compared to either therapy alone, leading to even long-term tumor-free survival in half of these leukemia-bearing mice." (PMID 27517629, 2016). "Several studies have demonstrated that IL-33 induces the expression of type-1 and -2 cytokines via the p38 MAPK pathway in innate lymphoid cells, natural killer cells, and leukemia cells." (PMID 37509127, 2023). "Previously, we identified interleukin-33 (IL-33) as a promoter of cell survival in a human AML cell line and primary mouse leukemia cells." (PMID 33324412, 2020). "Previously, we showed that IL1RL1, the receptor of IL-33, is highly expressed in leukemia cells expressing Cbfb-MYH11, and exogenous treatment with IL-33 promoted the survival of both primary mouse leukemia cells and human AML cell lines in vitro." (PMID 33324412, 2020). "We also found that IL-33 treatment increased the percentage of IFN-γ producing CD8+ T cells in both spleen and liver from leukemia-bearing mice by flow cytometry." (PMID 27517629, 2016). "However, the role of IL-33 in hematological malignancies such as leukemia remains largely unknown." (PMID 27517629, 2016). "Frequencies of total leukemic cells in IL-33 cit/cit KO LSCs recipients were significantly decreased compared to IL-33WT recipients at day 7 and day 14 following leukemia induction (not shown)." (PMID 40659660, 2025). "Previously, we demonstrated that exogenous IL-33 increases the expression of IL-6 using primary mouse leukemia cells expressing Cbfb-MYH11, which indicates that IL-33 may induce cytokine release to inhibit AML cell apoptosis." (PMID 33324412, 2020). "We found that IL-33 significantly decreased BrdU incorporation, as well as the percentage of cells in S-phase, indicating that IL-33 does not induce proliferation in Cbfb-MYH11+ leukemia cells." (PMID 30742053, 2019). "Thus, in this report we examined the expression of IL1RL1 in the LSC-enriched CSF2RB− population, and the effect of the IL1RL1 ligand, IL-33, on Cbfb-MYH11 expressing leukemia cells." (PMID 30742053, 2019). "To test this hypothesis, we treated mouse leukemia cells with the IL1RL1 ligand, IL-33, and performed serial replating experiments." (PMID 30742053, 2019). "The alarmin IL-33 and its receptor STimulation-2 (ST2) promote activation of tissue-regulatory T cells (Treg cells) and accelerate malignant progression in solid tumors, but their role in leukemia remains unclear." (PMID 40691440, 2025). "Thus, targeting of IL-33 or ST2 signaling is not expected to disrupt T cell reconstitution or graft-versus-leukemia (GVL) responses." (PMID 35503257, 2022). "Equal numbers of leukemia cells were plated in methylcellulose in the presence or absence of IL-33." (PMID 30742053, 2019). "Furthermore, other studies showed that the IL-33/ST2 axis increased effector T-cell responses to worsen acute GVHD, and ST2 blockade reduced GVHD severity and mortality while preserving graft-versus-leukemia activity." (PMID 27517629, 2016).
leukemia (continued). "Thus, the data indicate that the efficacy of exogenous IL-33 administration appears to depend in part on tumor immunogenicity, which was also supported by the fact that IL-33 treatment did not directly affect leukemia cell viability in vitro." (PMID 27517629, 2016). "However, recent data demonstrated the main mechanism of the immune escape is the tolerance of leukemia-specific CD8+ T cells, and IL-33-mediated actions on leukemic cells could be due to CD8+ T cells and MDSC populations as speculated and demonstrated in other tumor experimental models." (PMID 31652497, 2019). "After 6 hours of stimulation with IL-33, we observed significantly increased expression of Bcl-xl, TRAF-1, TRAF-2, and Mcl-1, but not Bcl-2 in leukemia cells." (PMID 30742053, 2019).
head and neck squamous cell carcinoma (17 papers, 2014 to 2025). A squamous cell carcinoma that arises from any of the following anatomic sites: lip and oral cavity, nasal cavity, paranasal sinuses, pharynx, larynx, and salivary glands. "A similar positive correlation between IL-33 and Tregs has also been identified in head and neck squamous cell carcinoma, which is further associated with a poor prognosis." (PMID 32363166, 2020). "For instance, in patients with head and neck squamous cell carcinoma and oral squamous cell carcinoma, intratumoral IL-33 has been shown to be expressed in cancer-associated fibroblasts (CAF)." (PMID 30416507, 2018). "Furthermore, IL-33 levels are significantly elevated in head and neck squamous cell carcinomas (HNSCC) and are closely associated with the depth of invasion and distant metastasis of HNSCC." (PMID 41272907, 2025). "In general, IL-33 as well as ST2 have been implicated in enhanced pathology and progression of colorectal, lung, breast and gastric cancer, as well as melanoma, head and neck squamous cell carcinoma and cholangiocarcinoma." (PMID 32363166, 2020). "However, the specific implications of IL-33/ST2 expression in Head and Neck Squamous Cell Carcinoma (HNSCC) prognosis are not fully understood." (PMID 40196136, 2025). "Similarly, in head and neck squamous cell carcinomas, administration of IL-33 promotes cancer cell migration and invasion through induction of epithelial-to-mesenchymal transition." (PMID 24778632, 2014). "IL-33-producing CAFS have been implicated as a critical mediator in CAF-induced invasiveness in head and neck squamous cell carcinoma (HNSCC)." (PMID 31231372, 2019). "Interestingly, the expression of the transcription factor MYC was downregulated in the presence of IL-33 in SCC-25 and Detroit 562 cells, two head and neck squamous cell carcinoma (HNSCC) cell lines." (PMID 38662248, 2024). "Furthermore, most head and neck squamous cell carcinoma (HNSCC) cases with a low invasion pattern grading score (IPGS) showed low or no expression of IL-33, whereas most HNSCC cases with high IPGS displayed abundant expression of IL-33 in CAFs and in cancer cells." (PMID 30483263, 2018). "IL-33 could support the expansion of ST2+Foxp3+ Treg cells, increasing the secretion of inhibitory cytokines IL-10 and TGF-β1 in ST2+Foxp3+ Treg cells and promoting their suppressive function in head and neck squamous cell carcinoma (HNSCC)." (PMID 34177907, 2021).
Hypertension (16 papers, 2016 to 2025). The presence of chronic increased pressure in the systemic arterial system. "When an analysis was performed on the association of IL–33 with different MetS components, we found that high levels of circulating IL–33 is a risk factor for MetS components; namely, hypertension, low HDL-c, and hypertriglyceridemia." (PMID 38255771, 2024). "Specifically, IL‐33 Signaling and Leukocyte Extravasation Signaling pathways were positively enriched, and activation of these pathways is associated with hypertension and microvascular complications." (PMID 38981849, 2024). "The results showed that higher tertiles of IL–33 serum levels were associated with higher odds of high blood pressure, low HDL-c, and hypertriglyceridemia (p-values < 0.01), and this remained significant in all models." (PMID 38255771, 2024). "We aimed to evaluate the association of IL-33 and its receptor levels with the occurrence of hypertension in angiotensin II (Ang II)-infused mice using microarray analysis and validated our results in human specimens." (PMID 31235844, 2019). "Additionally, having elevated levels of IL–33 was a risk factor for hypertension, low HDL-c, and hypertriglyceridemia." (PMID 38255771, 2024). "Because the IL-33 decoy receptor soluble ST2 (sST2) is widely recognized as a risk factor for hypertension, we hypothesized that the inhibition of sST2 by miR-202-3p was critical for the onset and development of EH." (PMID 32338289, 2020). "Given the alteration of the IL-33-sST2 pathway in hypertension, we conclude that sST2 acts as a risk factor for the occurrence of EH and may represent a promising novel marker for EH prediction." (PMID 31235844, 2019). "Hence, we assume that sST2, an IL‐33 decoy receptor, may function in hypertension risk by disrupting IL33‐ST2L signalling." (PMID 28121058, 2017). "We previously found that disruption of miR-202-3p mediated regulation of expression of soluble (s)ST2, a decoy receptor for interleukin (IL)-33, promotes essential hypertension (EH)." (PMID 32338289, 2020). "To investigate the relationship between IL-33 and hypertension in mice, we first infused male wild-type mice with Ang II (1500 ng/kg/min) for 1–7 days to induce hypertension and then performed microarray analysis." (PMID 31235844, 2019). "The IL-33/sST2 ratio was also significantly decreased in hypertensive patients compared to normal controls (hypertension: median 0.17 ng/ml, IQR: 0.13–0.24; control: median 0.20 ng/ml, IQR: 0.14–0.28; P < 0.001)." (PMID 31235844, 2019). "We used a binary logistic regression model to assess the risk of IL-33, SST2 and ST2L levels in serum or PBMCs in the occurrence of hypertension." (PMID 31235844, 2019). "The serum IL33/sST2 ratio was also significantly decreased in hypertensive patients compared to normal controls, supporting that the protective effects of IL-33 may be overwhelmed by concurrently elevated levels of sST2 when hypertension occurs." (PMID 31235844, 2019). "Further, hypertension-increased myocardial pressure also leads to elevated circulating IL-33." (PMID 31235844, 2019). "We speculated that when hypertension occurs, the vasculature undergoes mechanical stretching, and the expression of IL-33 in the cells increases." (PMID 31235844, 2019). "We aimed first to detect the expression of IL-33 in the aortas of mice with hypertension." (PMID 31235844, 2019). "Previous studies show that mechanical stress results in the release of bioactive IL-33 by cardiac endothelial cells and fibroblasts without cell death, and cardiac endothelial cells actively releases IL-33 resulting subsequent systemic inflammation in mice hypertension model." (PMID 29977243, 2018).